FGF21 (fibroblast growth factor 21)
Diseases named in the same sentence as FGF21 in open-access papers (continued):
Sharing a sentence is not in itself a finding about the gene and the disease.
Insulin resistance (continued). "Mechanisms that elevate either circulating FGF21 or adiponectin have been shown to increase energy expenditure, reduce adiposity, decrease insulin resistance and hyperglycaemia, and are associated with reduced cardiovascular disease events." (PMID 34762789, 2021). "We also measured levels of FGF21, which has been shown to be associated with insulin resistance and BAT activity." (PMID 34858338, 2021). "FGF21 has been linked to insulin resistance and gender differences, potentially driven by elevated circulating triglyceride levels, which have been described in CPHIV as well." (PMID 34972147, 2021). "Serum FGF21 levels were associated with metabolic risk factors in pregnancy, including insulin resistance, elevated TG levels, and decreased HDL." (PMID 34769010, 2021). "Circulating FGF21 concentration was positively associated with many clinical insulin resistance markers in pregnant women, and plasma FGF21 level at early pregnancy is considered as a potential predictor of GDM." (PMID 34912302, 2021). "Hepatic ER stress is closely linked with insulin resistance, and evidence indicates an alleviative effect of FGF-21 on hepatic ER stress." (PMID 32679813, 2020). "Elevated circulating FGF21 levels have been associated with conditions characterized by hepatic insulin-resistance (metabolic syndrome, nonalcoholic fatty liver disease (NAFLD), and T2DM)." (PMID 33204260, 2020). "We analyzed the role of FGF19, FGF21 and Klotho protein in children with normal body weight as well as in overweight and obese subjects and explored their associations with insulin resistance (IR) and metabolic syndrome (MS) and its components." (PMID 32546231, 2020). "FGF-21 regulates glucose homeostasis and lipid utilization, augments brown fat thermogenesis, and has been related to improved insulin resistance, weight loss and to the browning of WAT." (PMID 31191366, 2019). "In a recent study in mice, plasma FGF21 levels were reported to be an early predictive biomarker for the development of CVD risk factors such as insulin resistance, metabolic disturbance and cardiac FGF21 resistance." (PMID 31712677, 2019). "Studies in distinct HIV patient cohorts have consistently reported that elevated FGF21 levels are associated with indicators of insulin resistance, such as homeostatic model assessment of insulin resistance (HOMA-IR), insulinemia, and glycemia (6, –, 8, 16)." (PMID 29661866, 2018). "Impaired proteins ratio e.g. GGPPS, FAT, PTP-1B, GRK2, ATGL, FGF21 andPGC-1α presented in adipocytes and blood is responsible for causing insulin resistance and weight gain." (PMID 34466413, 2018). "FGF21, a member of the family of secreted FGFs, is associated with insulin resistance, an important aspect of the pathogenesis of PCOS." (PMID 30257687, 2018). "In conclusion, WPJ protected from diet-induced hepatic steatosis and insulin resistance, which was associated with the improved FGF21 resistance and lipid metabolism." (PMID 26914024, 2016). "Nevertheless, the possibility of including FGF-21 as a new marker to predict or measure insulin resistance in patients at high risk, such as those on PD, should be considered when designing further clinical studies to confirm and further explain these results." (PMID 26986485, 2016). "Larger studies with more patients are required to confirm the association between FGF21 and insulin resistance in AN." (PMID 27190511, 2016). "In insulin resistance and AD, FGF21 and adiponectin levels are implicated in increased cellular ceramide levels associated with cholesterol displacement in membranes with relevance to amyloidosis and AD." (PMID 28248224, 2016). "Fibroblast growth factor 21 (FGF21) plays an important role in the treatment of disease associated with muscle insulin resistance which is characterized by various factors, such as intramuscular triglyceride (IMT) content." (PMID 26703591, 2015).
Insulin resistance (continued). "FGF21-KO mice exhibited insulin resistance while being normoglycemic, associated with increases in beta-cell proliferation and insulin synthesis, acting as compensatory responses." (PMID 25811804, 2015). "We reported that serum FGF21 concentration was significantly associated with altered lipid profiles, especially with hypertriglyceridaemia, insulin resistance, metabolic syndrome, and ectopic fat deposition when adjusted for the body mass index." (PMID 23970879, 2013). "The second aim of the study was to investigate the possible association of muscle FGF21 mRNA with other measures of adiposity and insulin resistance, including peripheral insulin resistance by using an insulin clamp combined with stable isotopes." (PMID 23533568, 2013). "FGF21 is considered as a pharmacological candidate in conditions associated with insulin resistance." (PMID 23999826, 2013). "FGF21 serum concentrations showed a significant and positive association with insulin resistance and dyslipidemia including increased HOMA-IR, decreased adiponectin, and increased TG both in univariate and multivariate analysis." (PMID 24260557, 2013). "Only one trial evaluating serum FGF21 concentrations in GDM showed FGF21 was independently associated with markers of insulin resistance and an adverse lipid profile in pregnancy." (PMID 24260557, 2013). "New findings of this work were the changes of FGF-21 and its receptors in a new animal model where insulin resistance was induced by the combination of HFD, ApoE deficiency and adiponectin knockdown." (PMID 23152772, 2012). "Serum FGF21 levels are independently associated with markers of insulin resistance and an adverse lipid profile." (PMID 21331285, 2011). "The reduction of plasma FGF-21 levels was found to associate with the amelioration of insulin resistance shown by a significant relationship between ΔFGF-21 and M values in EHC." (PMID 22046277, 2011). "More important, to investigate the association of plasma FGF-21 and insulin resistance, multiple regression analyses in the subgroup of patients with EHC revealed a strong association ΔFGF-21 with M values (R2 = 0.565, B = −0.266, P<0.01)." (PMID 22046277, 2011). "The changes in plasma FGF-21 levels (ΔFGF-21) were positively associated with the amelioration of insulin resistance shown by the changes in M value." (PMID 22046277, 2011). "More importantly, the reduction of plasma FGF-21 levels was found to associate with the amelioration of insulin resistance shown by a significant relationship between ΔFGF-21 and M values in T2DM patients with EHC." (PMID 22046277, 2011). "More recently, a cross-sectional study also indicated that serum FGF21 concentration was associated with residual renal function and insulin resistance in end-stage CKD patients with long-term hemodialysis." (PMID 21525989, 2011). "Additionally, protein intake‐induced insulin resistance has been associated with altered FGF21 metabolism, suggesting a complex regulatory interplay between amino acid intake and FGF21 signaling." (PMID 41117265, 2025). "Oxidative stress is also a cause of insulin resistance (IR), and FGF21 can reduce oxidative stress." (PMID 40881124, 2025). "As mentioned in the Introduction section, aerobic exercise and FGF-21 can improve glucose homeostasis, regulate lipid utilization, increase thermogenesis in brown fat, and improve insulin resistance; they are also associated with browning of the white adipose tissue." (PMID 37108444, 2023). "Moreover, serum FGF21 levels increase during fasting in obese individuals and are associated with insulin resistance." (PMID 37576954, 2023). "On the other hand, the insulin resistance might cause resistance to FGF21, leading to compensatory upregulation of this antidiabetic adipocytokine." (PMID 37869250, 2023).
Insulin resistance (continued). "Scientific research on animal models shows that fibroblast growth factor 21 could stimulate macrophages to present an anti-inflammatory effect on adipocytes, which leads to a decreased risk of insulin resistance." (PMID 37892985, 2023). "In summary, impaired exercise-induced FGF21 secretion may be associated with factors such as hyperinsulinemia or hepatic insulin resistance in individuals with metabolic disruptions." (PMID 37755259, 2023). "Furthermore, both acute and chronic administration of FGF21 increased circulating adiponectin levels, and adiponectin deficiency diminished the metabolic effects of FGF21 on glucose tolerance and insulin resistance." (PMID 36263162, 2022). "This may be due to improvement in FGF21 signaling sensitivity similar to the effect on insulin resistance, which is ameliorated by loss of body weight." (PMID 35572519, 2022). "Alterations in FGF21 may be associated with the development of insulin resistance, metabolic syndrome and cardiovascular disease." (PMID 34019585, 2021). "Accumulating studies have demonstrated that the plasma levels of FGF21 increase in parallel with the severity of hepatic steatosis in humans, and are positively associated with TG, fasting insulin, and other insulin resistance indices, while negatively correlated with body mass index and HDL." (PMID 34944728, 2021). "Given the insulin-mediated induction and the progressive increase of serum FGF21 level with extent of impaired glucose-tolerance, these findings imply that insulin resistance is substantially associated with the elevated serum FGF21 concentration or the presence of FGF21 resistance." (PMID 33668309, 2021). "The mechanism underlying the dysfunction of the FGF21-adiponectin pathway in insulin resistance remains unclear." (PMID 34321008, 2021). "Loss of Fgf21 induces insulin resistance and islet dysfunction in mice." (PMID 32527043, 2020). "Because hyperglycemia, insulin resistance and hyperlipidemia are major risk factors for vascular endothelial dysfunction, we next examined whether FGF21 rescued impaired endothelial function in T2D2,3." (PMID 31511499, 2019). "Recent reports also showed the effect of FGF21 gene therapy on a high-fat-diet mouse model where treatment was associated with significant reductions in body weight, adipose tissue hypertrophy, insulin resistance, hepatic steatosis, inflammation, and fibrotic changes." (PMID 30384450, 2018). "Furthermore, FGF21 overproduction in healthy animals fed a standard diet prevented the increase in weight and insulin resistance associated with aging." (PMID 29987000, 2018). "Interestingly, FGF21 overexpression in normal mice fed with standard diet was also associated with the prevention of weight gain and insulin resistance related to aging." (PMID 30384450, 2018). "An association of insulin resistance between muscle and adipose tissue cannot be excluded, but weight reduction, increase in energy expenditure, and alternation of FGF21 expression by pemafibrate may contribute to improve glucose metabolism." (PMID 28195199, 2017). "In addition to AMPK, our results supported an important role for a PPARγ-FGF21 associated pathway in APL mediated- insulin resistance improvement." (PMID 27391974, 2016). "As KD is known to induce hepatic insulin resistance and to increase endogenous FGF21 levels, we investigated whether this could be associated with altered FGF21 signaling in addition to an inflammatory state." (PMID 25973847, 2015). "Circulating irisin and FGF21 have been linked statistically with indices of insulin resistance." (PMID 24603718, 2014). "Furthermore, FGF19 levels were negatively associated with insulin resistance and positively associated with adiponectin, in opposite with FGF21." (PMID 24260557, 2013). "In addition, we analyzed the association of serum FGF19 and FGF21 with markers of insulin resistance, glucose and lipid metabolism, as well as other adipokines." (PMID 24260557, 2013).
Insulin resistance (continued). "To test whether the association between insulin and FGF-21 mRNA in muscle reflect an association with peripheral or hepatic insulin resistance, we performed a euglycemic-hyperinsulinemic clamp with stable isotopes." (PMID 23533568, 2013). "Together, these observations also suggested that FGF-21 may be a therapeutic target for treatment of diabetes associated with insulin resistance." (PMID 23152772, 2012). "Furthermore, FGF-21 showed predictive capabilities for insulin resistance and dyslipidemia; serum concentrations ≥269 ng/mL were linked to an 8-fold heightened risk of insulin resistance, while levels of ≥275.7 ng/mL were connected to a 4.02-fold increased risk of dyslipidemia." (PMID 40559404, 2025). "Mechanisms studied to date suggest that NAFLD may increase the risk of developing T2DM by exacerbating hepatic insulin resistance, leading to the release of inflammatory mediators and diabetic hepatokines such as fetuin-A/B and fibroblast growth factor 21 (FGF21)." (PMID 38247531, 2024). "In contrast, recent studies have shown that FGF-21 exerts protective effects via attenuation of oxidative stress mediated by ROS, inflammation, vascular protective activities, lipotoxicity mainly associated with dysfunctional signaling in insulin resistance, and apoptosis." (PMID 35883694, 2022). "Pregnancy, as a temporary diabetogenic state mainly caused by insulin resistance, has circulating concentration of FGF-21 due to hepatic origin; therefore, it is possible that its regulation mechanisms might be modulated by different hormones of placental origin." (PMID 35883694, 2022). "In insulin resistance, mitochondrialrespiratory chain deficiency associated with a compensatory response in skeletalmuscle cells via increased expression and decreased degradation of FGF21 mRNAresults in enhanced mitochondrial function through a PGC-1a dependent pathway." (PMID 39077619, 2022). "Altogether, this study demonstrates that administration of AAV vectors that leads to therapeutically relevant levels of circulating FGF21 is safe in the long‐term in healthy and may be used to counteract the increase in body weight and insulin resistance associated with aging." (PMID 29987000, 2018). "FGF21 may have a potential role as a therapeutic agent for conditions associated with insulin resistance as it has been shown that administration of a recombinant form of this hormone in obese mice and diabetic monkeys improves insulin sensitivity, body weight, and lipid profile." (PMID 23999826, 2013). "However, as sepsis is associated with insulin resistance, we can also hypothesize that the increase in plasma FGF21 observed in subjects with sepsis and SIRS might also be due, at least partly, to insulin resistance." (PMID 23999826, 2013). "Taken together, the higher levels of plasma FGF21 in women with GDM could be a compensatory response to the underlying differences in maternal physiology such as higher insulin resistance at the start of the pregnancy and/or poorer reserve in insulin secretion capacity in GDM subjects." (PMID 23755203, 2013). "Therefore, further prospective studies are warranted to determine whether elevated FGF21 is directly caused by sepsis or is a marker of the insulin resistance present during sepsis." (PMID 23999826, 2013). "In this study, by using the ApoE−/− mice, we hypothesized that 1) the combination of HFD, hyperlipidemia, and adiponectin knockdown may cause more severe insulin resistance and 2) that the insulin resistance ameliorating effects of liraglutide was, at least in part, due to increased FGF-21 activity." (PMID 23152772, 2012). "In parallel, carriers of AG genotype of FGF21 rs838133 exhibited a higher propensity for progression to MASLD (AOR: 18.622; 95% CI: 1.619-214.169, P = 0.019) and G allele accompanied by greater insulin resistance and unfavorable lipid profiles." (PMID 41975319, 2026).
Insulin resistance (continued). "FGF21 expression and levels are influenced by diet, nutritional status, hormones, and activity of related transcription factors.FGF21 has been shown to have a positive role in ameliorating insulin resistance and to mediate glucagon action." (PMID 40881124, 2025). "⁃ Palmitate-induced insulin resistance is linked to the loss of myotubes and the low expression of myonectin, FNDC5, and FGF21." (PMID 40741175, 2025). "In obese mice, FGF21/sTGFBR2 improved insulin resistance and hyperlipidemia more dramatically at warmer temperatures." (PMID 40663389, 2025). "FGF21 analogs regulate energy and lipid metabolism, helping to reduce liver fat and improve insulin resistance." (PMID 41262444, 2025). "In summary, FGF21 can improve insulin resistance by improving insulin signaling and affecting its downstream pathway." (PMID 40881124, 2025). "The targeted deletion of autophagy-related gene 7 (ATG7) in skeletal muscle inhibits mitophagy and induces FGF21 secretion, thereby preventing insulin resistance." (PMID 40881124, 2025). "The yellow cluster identifies FGF21 as hepatoprotective, countering fetuin-A-induced insulin resistance, while NRG4 connects exercise to lipid oxidation." (PMID 40868109, 2025). "In lipodystrophic mice on a high-fat diet, combination therapy required adipose tissue to improve insulin resistance at 30°C, whereas FGF21 alone improved insulin resistance at 22°C." (PMID 40663389, 2025). "At the same time, the multiple effects of FGF21 and CNS coordinate with each other to regulate body metabolism and reverse insulin resistance." (PMID 40881124, 2025). "We were particularly interested in effects of gene therapy on insulin resistance, hepatic steatosis, and bone mass, as these variables have been shown to be altered with FGF21 treatment." (PMID 40663389, 2025). "This review summarizes the studies of recent years, detailing recent advances in the study of FGF21 in insulin resistance, and develops the new potential of FGF21 for the treatment of IR." (PMID 40881124, 2025). "activation of AMPK signaling indirectly increases the expression of GLUT4 to increase glucose uptake and improves IR, and FGF21 inhibits mTOR signaling to ameliorate insulin resistance due to impaired insulin signaling." (PMID 40881124, 2025). "In our longitudinal study, we identified a sharp increase in FGF21 early after surgery concomitant with a decrease in insulin resistance and serum leptin levels." (PMID 39885510, 2025). "Reports suggest that FGFs modulate insulin resistance induced by high-fat diets, fasting glucose, and triglyceride levels, with FGF-21 being the most extensively studied member of this family." (PMID 40943671, 2025). "AhR activation can exacerbate insulin resistance by promoting proinflammatory signaling or potentially improve it by activating metabolic regulators such as FGF21." (PMID 41440753, 2025). "Optimized LDR regimens and their combination with fibroblast growth factor-21 (FGF21) further amplify these systemic benefits by addressing key factors such as dyslipidemia, insulin resistance, and diabetes-induced renal pathology." (PMID 40282189, 2025). "In individuals with MUO, elevated FGF21 levels indicate a state of FGF21 resistance, where impaired signaling contributes to adipose dysfunction and insulin resistance." (PMID 41008585, 2025). "A serum FGF-21 level of ≥269 ng/mL indicated a sensitivity of 67% and a specificity of 80% for identifying insulin resistance." (PMID 40559404, 2025). "Some organokines have protective effects (e.g., FGF-21, irisin, and klotho), while others, such as myostatin and fetuin-A, exacerbate insulin resistance and fibrosis." (PMID 41373697, 2025). "AhR activation in the liver induces the endocrine hormone FGF21, which protects against obesity and insulin resistance, uncoupling hepatic steatosis from insulin resistance." (PMID 41440753, 2025).